IL33 (interleukin 33)
Diseases named in the same sentence as IL33 in open-access papers (continued):
Sharing a sentence is not in itself a finding about the gene and the disease.
liver fibrosis (continued). "However, another study showed that IL-33 deficiency did not affect the severity of liver inflammation or liver fibrosis in a mouse model of diet-induced steatohepatitis." (PMID 39350187, 2024). "Many reports have shown that IL-33 is highly expressed in a variety of chronic inflammatory conditions, such as chronic hepatitis B, liver fibrosis, and precancerous lesions, suggesting that IL-33 may play an important role in the progression of inflammation to tumors." (PMID 37507682, 2023). "However, it was suggested that ST2 might be employed as a Th1 cell activation marker that may explain the IL-33/ST2 role in progression of liver fibrosis." (PMID 35056005, 2022). "Targeting ILC2s and modulation of IL-33 may be therapeutic strategies for treating liver fibrosis." (PMID 35574038, 2022). "However, in liver fibrosis, the main source of IL-33 has been reported to be stressed hepatocytes." (PMID 33311540, 2020). "Our data might therefore reconcile with an increase of IL-33 in the fibrotic liver and not the blood to associate/mediate the progression of liver fibrosis." (PMID 31849991, 2019). "The IL-33 expression levels in the liver biopsy IHC (relative expression 5.4 ± 1.0 vs. 3.0 ± 0.5, p = 0.0229) and serum (305.1 ± 102.2 vs. 131.1 ± 32.3 pg/ml, p = 0.0502) were significantly higher in patients with a Masson score of 3, indicating that IL-33 can be related to liver fibrosis stage." (PMID 31632941, 2019). "Similar observations have been made for IL-33, with elevated levels of IL-33 detected in lung tissues during fibrosis or intestinal epithelium of patients with pulmonary fibrosis or fibrotic colitis, respectively, and in the liver of mice with hepatic fibrosis." (PMID 31354734, 2019). "Therefore, we hypothesize that the elevated IL-33 in BA livers associates with ST2 receptor and subsequently stimulates MC function, ultimately contributing to the progression of liver fibrosis." (PMID 31632941, 2019). "tTG, IL-33 or ST2 might be promising drug targets against liver fibrosis induced by Sj infection." (PMID 31200771, 2019). "Indeed, IL-33 has shown potential liver fibrosis promoting effect." (PMID 30405626, 2018). "However, it remains unclear whether the IL-33 elevation is a result of or relevant to liver fibrosis." (PMID 26549942, 2015). "To address this, we must examine whether Il33−/− and St2−/− mice are resistant to liver fibrosis." (PMID 26549942, 2015). "In addition, IL-33 levels have been positively correlated with liver fibrosis in mice and humans." (PMID 23423835, 2012). "Following targeted suppression of the IL-33/ST-2 signaling pathway in combination with ABZ administration, hepatic fibrosis in liver and therapeutic outcomes were assessed through Masson staining, western blot analysis, and liver index measurements." (PMID 41933369, 2026). "The IL-33-mediated Th2 immune response promotes HSCs proliferation, TGF-β synthesis, and collagen deposition, with overexpression of IL-33 inducing liver fibrosis." (PMID 39995661, 2025). "In patients with chronic liver disease, IL-33 acts as a chemotactic agent for Th2, inducing type 2 polarization of CD4+T cells, thereby promoting liver fibrosis, Th2 cytokines, such as IL-6, IL-4, and IL-13, promoting the formation of fibrosis." (PMID 39925809, 2025). "Studies have confirmed significantly elevated levels of IL-33 and ST2 mRNA in the serum of patients and mice with liver fibrosis compared to those in controls." (PMID 39689154, 2025). "IL-33 released by HSC activates the positive tendency of ST2, thereby promoting the progression of liver fibrosis." (PMID 39925809, 2025). "IL-33 targets innate lymphoid cell (ILC) 2 and T helper 2 (Th2) cells, which contribute to liver fibrosis by inducing the expression of IL-1385,87." (PMID 40579434, 2025). "Based on the physiological role of the IL-33/ST2 axis, sST2 is of particular interest in the assessment of liver fibrosis." (PMID 38291388, 2024).
liver fibrosis (continued). "Increased levels of IL-33 are related to liver damage in CHC patients and to the development of HCV/HBV infection into liver fibrosis." (PMID 39201990, 2024). "In human fibrotic liver disease, the IL-33/ST2 signalling pathway is upregulated, it induces hepatic stellate cell activation and as a consequence facilitates progression to liver fibrosis." (PMID 38291388, 2024). "However, there is still little clarification, and further studies are needed on the role of IL-33 in the activation and differentiation of macrophages involved in liver fibrosis during S. mansoni infection, which may be the key point for understanding the development of this process." (PMID 37373379, 2023). "Additionally, IL-33 also could directly activate HSCs to drive hepatic fibrosis." (PMID 32765518, 2020). "In this study, we observed that tTG plays an important role in regulating IL-33/ST2 expression and alleviating the severity of liver fibrosis following Sj challenge." (PMID 31200771, 2019). "As reported, IL-33 was critical for hepatic accumulation of ILC2 with high expression of ST2, and ILC2 mediated hepatic fibrosis resulting from Sm eggs challenge." (PMID 31200771, 2019). "The inhibition of tTG activity through cystamine administration or gene knockout alleviated the level of TLR4, NF-κB pathway molecules, IL-33/ST2, and the severity of liver fibrosis resulting from Sj infection." (PMID 31200771, 2019). "After being activated by IL-33, hepatic MC releases numerous inflammatory mediators, among which transforming growth factor-beta 1 (TGF-β1) and IL-13 are correlated with liver fibrosis." (PMID 31632941, 2019). "Treatment with IL‐33 attenuated hepatic steatosis, systemic insulin resistance, and glucose intolerance and reduced serum ALT activity while aggravating hepatic fibrosis." (PMID 30478965, 2019). "Hepatic fibrosis was assessed by ultrasound according to WHO Niamey guidelines and plasma levels of Interleukin 33 were determined by ELISA." (PMID 31849991, 2019). "The study also revealed that in hepatic fibrosis, IL-33 expression was elevated, and excess ECM deposition was sufficiently driven by IL-33 alone in the liver." (PMID 29180837, 2017). "The major finding of our study was that IL-33 treatment attenuated diet-induced hepatic steatosis and reduced serum ALT levels, but aggravated hepatic fibrosis." (PMID 27172901, 2016). "C57Bl/6 mice fed HFD developed liver fibrosis and increased hepatic procollagen and TGF-β mRNA expression, and IL-33, IL-13 and TGF-β levels in liver homogenates, while BALB/c mice fed HFD had scarce collagen deposition in liver." (PMID 26218873, 2015). "IL-33, along with Connective Tissue Growth Factor (CTGF, secreted by fibroblasts after activation by TGF-β1), is an important proinflammatory cytokine that contributes to increased oxidative stress and liver fibrosis." (PMID 41517312, 2025). "In a schistosome mouse model, both IL-33 and ST2 levels were elevated, suggesting that the IL-33/ST2 axis might serve as a therapeutic target for liver fibrosis." (PMID 39995661, 2025). "More importantly, current results showed that an increase in IL-33 levels did not change by progress of the disease from chronicity to hepatic cancer; however, it increased significantly by liver fibrosis." (PMID 35056005, 2022). "Importantly, increased IL-33 levels are related to liver damage in CHC patients and to the development of HCV/HBV-induced liver fibrosis." (PMID 35056005, 2022). "However, some studies have found that the IL-33/ST2 axis can also promote Th2-type responses and hepatic stellate cell activity, promoting the progression of liver fibrosis due to chronic damage, which is a protective mechanism." (PMID 35911735, 2022). "A significant correlation was found between levels of IL-33 and TGF-β levels, which may explain its role in liver fibrosis." (PMID 35056005, 2022).
liver fibrosis (continued). "It has previously been demonstrated that IL-33 participates in liver fibrosis regardless of different types of liver fibrosis." (PMID 36271450, 2022). "An approach aimed at the IL-33/ST2 path could be a potential therapeutic target for human patients suffering from chronic hepatitis and liver fibrosis." (PMID 33841164, 2021). "Thus, critical roles for IL-33 in activation of Th2 immune responses via cytokines IL-4, IL-6 and IL-13 have been demonstrated in the pathogenesis of HSEC proliferation and liver fibrosis in mouse models." (PMID 32486265, 2020). "However, another study demonstrated an overlapping role of IL-33, IL-25, and TSLP in a schistosome-induced lung granuloma and liver fibrosis model." (PMID 32132991, 2020). "Importantly, we further demonstrated that tTG activity inhibition or tTG knockout leads to a decreased expression level of IL-33/ST2 and alleviated severity of liver fibrosis." (PMID 31200771, 2019). "We tested whether tTG regulates IL-33 and ST2 expression during liver fibrosis induced by Sj infection either using tTG knock-out mice or by inhibiting tTGʼs enzymatic activity." (PMID 31200771, 2019). "However, IL-33 promotes Th2 reactions and HSC activity, facilitating the progression to liver fibrosis." (PMID 29180837, 2017). "However, when liver injury is chronic, IL-33 promotes Th2 reactions and hepatic stellate cell (HSC) activity, facilitating progression to liver fibrosis." (PMID 29180837, 2017). "Although earlier we introduced the idea that IL-33 could alleviate HFD-induced hepatic steatosis and insulin resistance, it has been verified that in diet-induced NASH, IL-33-mediated aggravation of hepatic fibrosis was dependent on the ST2 signalling pathway." (PMID 29180837, 2017). "Treatment with IL-33 attenuated diet-induced hepatic steatosis and reduced activities of ALT in serum, as well as ameliorated HFD-induced systemic insulin resistance and glucose intolerance, while aggravated hepatic fibrosis in diet-induced NASH." (PMID 27172901, 2016). "When fed with HFD, treatment with IL-33 aggravated hepatic fibrosis in wild-type mice, but did not affect fibrosis in ST2 knockout mice." (PMID 27172901, 2016). "IL-33, a cytokine belonging to the IL-1 superfamily, along with its cognate receptor serum stimulation 2 (ST2) were reported to be upregulated in the liver of patients and mouse models of NASH (HFD, MCD), and to be increased with the progression of the disease to hepatic fibrosis." (PMID 40794228, 2025). "Therefore, IL13, IL-33, and TGF-β seem to cooperate, to an extent, for promoting hepatic fibrosis in MASLD and may play a more adverse role in advanced stages of the disease." (PMID 40794228, 2025). "Thus, the current study provides evidence that supports the role of the IL-33/ST2 pathway in liver-repairing mechanisms and the appropriate organisation of collagen around parasite eggs, participating in S. mansoni-induced liver fibrosis and controlling disease severity." (PMID 37373379, 2023). "Also, due to the fact that they are able to process extracellular matrix and activate pro-fibrotic cytokines such as IL-1β and IL-33 (Interleukin-33), PR3 and NE might play an important role in the mechanisms of liver fibrosis." (PMID 31046673, 2019). "In conclusion, chymase is a double-edged sword with regard to the development of liver fibrosis; on the one hand, it cleaves/activates pro-fibrotic proteins, such as angiotensin I, MMP-9, TGF-β, and type I pro-collagen, and on the other hand, it can degrade pro-fibrotic IL-33 and HMGB1." (PMID 31766207, 2019). "Therefore, we aimed to investigate the function of the IL-33/ST2 receptor signaling axis in BA patients compared to cholestasis infants with similar symptoms; and to elucidate its correlation with liver fibrosis progression in BA patients of different prognosis." (PMID 31632941, 2019).
liver fibrosis (continued). "It was suggested that the concurrent pro-fibrotic effect of IL-33 might be mediated by induction of IL-13 expression in ILC2 as shown in murine models of hepatic fibrosis, in which ILC2-derived IL-13 activated HSC, the key drivers of hepatic fibrosis." (PMID 30213101, 2018). "Thus, it is possible that the extracellular form of IL-33 triggers fibrosis, as IL-33-induced liver fibrosis is totally reversed in ST2 deficient mice, whereas the hydrodynamic delivery of intracellular IL-33 in IL-33 KO mice does not induce liver disease." (PMID 28611297, 2017). "IL-33 may represent a new and easy-to-detect biomarker for the diagnosis of liver damage in CHC patients, as it appears to be modulated in parallel with biochemical and histologic parameters, such as ALT levels and liver fibrosis." (PMID 23423835, 2012). "Moreover, good evidence was shown in investigations of serum IL-18 and IL-33 in distinguishing BA from healthy controls, serum IL-18 for prognosis of post-KPE persistent jaundice, and serum hyaluronic acid and MMP-7 for prognosis of post-KPE significant liver fibrosis." (PMID 34083585, 2021). "We did not use IL-13 or IL-33 knockout mice or neutralizing antibody to verify that IL-13 or IL-33 play a role in liver fibrosis during Sj infection as several publications have already reported that IL-13 and IL-33 mediate liver fibrosis during Schistosoma infection." (PMID 31200771, 2019). "Finally, we focused on the immune cell targets of IL-33, i.e. ST2-expressing cells; particularly Treg ST2+ cells, which display the highest expression of the IL-33 receptor in experimental acute hepatitis, and ILC2, which are essential downstream effectors in IL-33-mediated liver fibrosis." (PMID 28611297, 2017). "Contrarily to IL-33, current findings indicate that serum levels of IL-17 and IL-25 did not increase in HCV patients with higher viral loads or liver fibrosis." (PMID 35056005, 2022). "IL-33 is pro-fibrogenic, as its hepatic expression is sufficient to drive severe liver fibrosis through ILC2-derived IL-13; which is further demonstrated by a strong reduction of experimentally-induced liver fibrosis in mice lacking IL-33." (PMID 28611297, 2017). "However, this does not indicate whether myofibroblast-derived IL-33 initiates and/or exacerbates liver fibrosis, because we do not know whether or how the myofibroblasts undergo the necroptotic or pyroptotic cell death that allows liberation of intracellular IL-33." (PMID 26549942, 2015). "Moreover, because only a few publications were included in the analysis of BA diagnosis based on serum IL-33 and prediction of post-KPE significant liver fibrosis with APRi, the threshold effect and SROC curves were not obtained in either analysis." (PMID 34083585, 2021). "Hepatic fibrosis induced by S. mansoni is not affected by the lack of TSLP, IL-25, and IL-33 signaling individually, but disruption of signaling by all three mediators reduced hepatic fibrosis, eosinophils, and innate lymphoid cell (ILC)-2 in the liver of mice." (PMID 32922381, 2020). "However, the relationship between tTG, IL-33/ST2, and liver fibrosis during Schistosoma infection has not been established." (PMID 31200771, 2019). "In our research, IL-33 was not significantly upregulated, whereas IL-13, TGF-β1, and type I collagen were highly expressed after infection, indicating that there are alternative pathways that induce overexpression of IL-13 and TGF-β1 and mediate liver fibrosis in BA." (PMID 34858903, 2021).
inflammatory bowel disease (74 papers, 2010 to 2026). A spectrum of small and large bowel inflammatory diseases of unknown etiology. "Investigation of ST2/IL-33 signaling has been implicated in various inflammatory diseases such as cardiac disease, inflammatory bowel diseases, and type 2 diabetes." (PMID 36080225, 2022). "IL-33 plays an important role in the regulation of host immune responses and has been associated with human inflammatory bowel diseases (IBD), as well as tumors." (PMID 30547011, 2018). "Specifically, IL-33-deficient mice had more segmented filamentous bacteria, which were found also in a mice model of inflammatory bowel diseases." (PMID 30577568, 2018). "We report here that peritoneal injection of IL-33 exacerbated inflammatory bowel disease in IL-10-deficient (IL-10−/−) mice, whereas IL-33-treated IL-10-sufficient (wild type) mice were protected from the disease induction." (PMID 24491821, 2014). "The IL1RL1/IL33 signaling axis was implicated in inflammatory bowel disease (IBD) for the first time in two recent studies characterizing IL1RL1 and IL33 protein and mRNA expression in IBD patients." (PMID 21629437, 2010). "Dysregulation of ST2/IL-33 signaling and sST2 production have been implicated in a variety of inflammatory diseases such as cardiac disease, inflammatory bowel disease (IBD), graft-versus-host disease (GVHD), small bowel transplant rejection, and type 2 diabetes." (PMID 28484466, 2017). "Polymorphisms in the Il33 gene are detected in patients with Alzheimer's disease and Inflammatory Bowel disease (IBD) suggesting that a complete or partial loss of function leads to exacerbated disease." (PMID 30949175, 2019). "An association between IL33 rs3939286 and some immune-mediated diseases such as inflammatory bowel disease (IBD) has been described." (PMID 26571131, 2015). "IL-33 shows a high level in the inflamed lesions of patients with inflammatory bowel disease (IBD) and acts as either an inflammatory driver or an alarmin." (PMID 37889976, 2023). "IL-33, belonging to the IL-1 cytokine family, exerts a vital role in various inflammatory bowel diseases including UC." (PMID 37693835, 2023). "On the other hand, IL-33 stimulates B cells to generate IL-10-producing CD19+CD25+CD1dhighIgMhighCD5−CD23−Tim-1- regulatory B cells to protect mice from inflammatory bowel disease." (PMID 36291105, 2022). "IL-33 has been implicated in chronic inflammatory diseases of the gastrointestinal tract where fibrosis has a pathogenic role, such as eosinophilic oesophagitis (EoE) and inflammatory bowel disease (IBD)." (PMID 38566909, 2022). "IL-33 expression is increased in the intestinal mucosa and barrier of patients with inflammatory bowel disease." (PMID 36291105, 2022). "In the last years, IL-33 has become a novel focus of attention in inflammatory disorders, such as inflammatory bowel disease, infectious disease, and autoimmunity." (PMID 33133101, 2020). "The IL-33-IL-33R/ST2 axis is involved in inflammatory bowel diseases (IBD) and has a regulatory role in experimental mouse models of IBD." (PMID 31057534, 2019). "Several studies have shown the immunoregulatory effect of IL-33 on regulatory cells in the mouse model of inflammatory bowel disease and in mice following cardiac transplantation." (PMID 30498495, 2018). "There are only few studies which showed IL-33 immunoregulatory effect on this cell subset in mouse model of inflammatory bowel disease and in mice after heart transplantation." (PMID 27761063, 2016). "For example, a parasitic nematode infection can trigger the release of interleukin 33 (IL-33) as a defence mechanism; in turn, IL-33 might contribute to inflammatory bowel disease, which might lead to a decreased lifespan." (PMID 37434526, 2023). "In addition, IL25 and IL33 are also secreted by ILC2s, mediating the fibrosis pattern in pulmonary fibrosis and raising questions regarding the stenosis inducer subset of inflammatory bowel diseases (IBD)." (PMID 33673676, 2021).